BRCA1 (BRCA1 DNA repair associated)
Diseases named in the same sentence as BRCA1 in open-access papers (continued):
Sharing a sentence is not in itself a finding about the gene and the disease.
cancer (continued). "In pediatric cancers, germline predisposition or somatic alterations in BRCA1/2 genes are infrequent and only a small fraction (2.29%) of tumors showed SBS3 activity in this analysis, but without the complementing indel signature ID6." (PMID 36702933, 2023). "PARP inhibition is synthetically lethal in an HR-deficient condition; for this reason, PARPi is used to treat cancers with BRCA1/2 mutations." (PMID 37760968, 2023). "Fascinatingly, BRCA1-mutated cancer cells display accumulation of cytoplasmic RNA-DNA hybrids, which are products of R-loop processing." (PMID 38139802, 2023). "In this review, we will first summarize the clinical outcomes of the four FDA-approved PARPi in treating BRCA1/2 deficient cancers." (PMID 37035242, 2023). "Examples include PARP inhibitors such as olaparib, which have been shown to be effective in treating cancers with BRCA1 and BRCA2 mutations among others." (PMID 38163482, 2023). "The BRCA1 gene encodes the 1863 amino acid sequence and more than 200 different germline mutations of this gene are related to cancer progression." (PMID 37509303, 2023). "While the simultaneous presence of PVs in two distinct cancer-associated genes is uncommon, our study's unexpected discovery of 31 co-occurring BRCA1/2 variants challenges this notion." (PMID 37804357, 2023). "For example, poly (ADP-ribose) polymerase (PARP) inhibitors (PARPi) are used in cancer patients with the BRCA1/2 mutation, which will be discussed in the later section." (PMID 37760968, 2023). "In the case of early cancers in women with a pathogenic BRCA1/2 variant, the predominant site of the origin of the disease is the fimbriae or the distal part of the tube." (PMID 36837501, 2023). "A theoretical interest in PARP inhibition in ATM-mutated cancers stems from the involvement of the kinase in the same HR repair pathway as BRCA1 and BRCA2." (PMID 36975505, 2023). "BRCA1 is a key DNA-repair protein, and its functional loss leaves some cells highly vulnerable to DNA damage, including damage that triggers cancer." (PMID 37224529, 2023). "Most of these cancer-associated missense mutations abolish the phosphate moiety binding capability, resulting in defective recruitment of BRCA1 to DNA lesions for HR repair." (PMID 37789001, 2023). "Cancer cells with harmful variants in BRCA1/2 are unable to repair DNA double-strand breaks and they are heavily rely on single-strand break repair pathways." (PMID 37656691, 2023). "Approximately 5–10% of the cancer patient population harbour germline genetic alterations in cellular DNA repair genes associated with predisposition to malignancies, of which BRCA1/2 are often reported and primarily associated with breast and ovarian cancers." (PMID 37046302, 2023). "Apart from PVs of medium-high penetrance (MHPVs) in BRCA1/2, testing also includes low-penetrance alleles, which have been frequently reported in patients with cancer, for example, APC c.3920T>A and CHEK2 c.1283C>T." (PMID 38201524, 2023). "Patients with BRCA1/2 mutations and their families can benefit from cancer risk reduction or early cancer detection strategies, such as double mastectomy or high-risk follow-up for BC and bilateral salpingo-oophorectomy for OC." (PMID 37664050, 2023). "While cancers arising in BRCA1/2 mutation carriers certainly show marked sensitivity to platinum-based chemotherapeutic regimens and immunotherapies, there is still some heterogeneity in regards to treatment response." (PMID 36831687, 2023). "Due to their HR defect, BRCA1/2-deficient cancers are sensitive to poly(ADP-ribose) polymerase inhibitors (PARPis), but they eventually acquire resistance." (PMID 37209095, 2023).
cancer (continued). "Multigene panel testing, as a regular practice, will likely continue to detect germline variants in other non-BRCA1/2 genes, which are individually rare but confer a modest increase in cancer risk with questionable associated clinical significance." (PMID 37347260, 2023). "Alterations in BRCA1/2 genes are associated with marked genomic instability and cancer predisposition." (PMID 37783689, 2023). "Since that publication, several other studies investigated the prevalence of the methylation of BRCA1 promoter in peripheral blood and its association with cancer risk, but the results of those studies were frequently discrepant." (PMID 37752189, 2023). "It has been demonstrated that for BRCA1 PV carriers, the disease risk displays a polygenic pattern and mode of inheritance, with an elevated cancer risk observed in individuals with an increased number of affected first- and second-degree relatives." (PMID 37296919, 2023). "Several PARP1 inhibitors have been FDA-approved for the treatment of DNA damage repair (DDR)-deficient cancers including those harboring BRCA1/2, ATM, and RAD51C mutations." (PMID 37821462, 2023). "For germline BRCA1 mutation carriers, cancer is often initiated by the sporadic loss of the wild-type BRCA1 allele." (PMID 37815460, 2023). "In the presence of BRCA1/2 mutations, cancer cells are unable to properly repair DNA damage, leading to uncontrolled proliferation and tumor development." (PMID 37108398, 2023). "The prevalence of BRCA1 gene mutations has been studied widely and in many countries, mostly in women affected with cancer." (PMID 38031144, 2023). "Germline pathogenic variants in BRCA1/2 genes result in increased risks of various cancers via an autosomal dominant pattern of inheritance." (PMID 36861435, 2023). "A relevant example of such functional interactions is represented by the ability of SETX to interact with BRCA1, a tumor-suppressor gene mutated in breast, ovarian and other types of cancers." (PMID 37147318, 2023). "Studies have reported that ETS expression sensitises cancer cells to PARP-1 inhibition as much as or more than BRCA1/2 deficiency." (PMID 37686260, 2023). "Individuals with HBOC are heterozygously mutated in either BRCA1 or BRCA2, and the cancer‐initiating cells in these patients usually undergo loss of the wild‐type BRCA1/2 allele, leading to homologous recombination defects." (PMID 36345163, 2023). "In summary, this study investigated the cancer spectrum and risk in relatives of BRCA1/2 carriers in a Chinese population." (PMID 36861435, 2023). "A series of studies on the spectrum and risk of cancer in BRCA1/2 pathogenic variant carriers (hereafter referred to BRCA1/2 carriers) have been conducted." (PMID 36861435, 2023). "Detecting BRCA1/2 mutations allows crucial and challenging decisions regarding cancer prevention or risk reduction, early detection and pharmacological management." (PMID 37664050, 2023). "Although olaparib is widely used in the chemotherapy of cancers with BRCA1/2 mutations, drug resistance still poses a significant challenge." (PMID 38067284, 2023). "TRIP13 overexpression is common in BRCA1-deficient cancers, confers PARP inhibitor resistance, and correlates with poor prognosis." (PMID 38067275, 2023). "The lifetime risk of developing breast, ovarian and other cancers is significantly increased in BRCA1 and BRCA2 mutation carriers." (PMID 37713444, 2023). "Olaparib suppresses DNA damage repair by inhibiting the poly ADP ribose polymerase (PARP), especially in cancers with BRCA1/2 mutations or the BRCA-ness phenotype." (PMID 38067284, 2023).
cancer (continued). "Long-term data from clinical trials of various PARP inhibitors demonstrate a sustained response primarily in cancer patients with BRCA1/2 mutations, albeit the majority of patients inevitably develop resistance to platinum-based and/or PARP inhibitor therapy." (PMID 38115743, 2023). "This retrospective review reports a comprehensive population-based dataset of 156 females at very high cancer risk due to a BRCA1/2 PV." (PMID 37887578, 2023). "Taken together, downregulation of ZNF251 was associated with resistance to olaparib and/or platinum derivatives in breast and/or ovarian BRCA1-mutated cancer cells." (PMID 37066268, 2023). "In cancers containing insufficient HR, resulting from mutations in necessary pathway proteins such as BRCA1 and BRCA2, cells treated with PARP inhibitors are forced to rely on NHEJ to repair DSBs." (PMID 37508568, 2023). "Most previous studies involving BRCA-associated cancer have focused on BRCA1/2 carriers; however, a limited number of studies have examined the cancer risk and spectrum in relatives of BRCA1/2 carriers." (PMID 36861435, 2023). "Similar results were observed for the BRCA1‐mutated cancer cell line SUM149PT, in which otherwise sublethal concentrations of olaparib (≤ 10 nM) were selectively toxic in BRCA1‐deficient cells in the presence of 0.5 μM CldU." (PMID 37492888, 2023). "Mechanistically, we discovered that ZNF251 haploinsufficiency leads to constitutive stimulation of DNA-PKcs-dependent non-homologous end joining (NHEJ) repair of DSBs and DNA-PKcs-mediated fork protection in BRCA1-mutated cancer cells (BRCA1mut + ZNF251KD)." (PMID 37066268, 2023). "The study of BRCA1/2 variants in these patients is crucial to identify candidates for these treatments, but is also important to manage their future cancer risks." (PMID 37664050, 2023). "Unfortunately, BRCA1/2-deficient cancer cells very often acquire drug resistance, by means of different mechanisms, including reversion of BRCA1/2 mutations, restoration of HR and of replication fork stability." (PMID 37783689, 2023). "The efficacy of olaparib monotherapy in cancers harboring BRCA1/BRCA2 mutations underscores the significance of leveraging known DDR deficiencies to elicit distinct effects between malignant and healthy tissues." (PMID 38115743, 2023). "Evidences have demonstrated that deleterious BRCA1/2 variants contribute to the development of other types of cancers, including pancreatic, stomach and male BC." (PMID 37046793, 2023). "The risk of TNBC is higher in certain ethnic groups, such as Latin, African, and African-American women, as well as women with breast cancer 1 (BRCA1) gene mutations." (PMID 36678877, 2023). "Although ubiquitously expressed, the reason cancer develops in a tissue-specific manner in BRCA1/2 mutation carriers is not fully understood." (PMID 38203374, 2023). "The median age for cancer diagnosis across the BRCA1/2 mutation carriers was 46 years, in the CHEK2 group it was 42.5 years, 44.8 years for ATM, 48.6 years for PALB2, 44 years for MUTYH, and 45.6 years for BLM." (PMID 38201513, 2023). "A BRCA1 variant that results in loss of function in DNA repair should indicate higher likelihood of cancer predisposition." (PMID 37917606, 2023). "Inheritance of a germline mutation of the BRCA1 gene predisposes with high penetrance to breast, ovarian, and other forms of epithelial carcinoma." (PMID 37373065, 2023). "Further, genetic variants such as the single nucleotide polymorphism p.Ala247Ser, and other XRCC4 mutations, contribute to cancer susceptibility in non‐BRCA1/2 breast cancer, oral cancer, and hepatocellular carcinoma in humans." (PMID 35000298, 2022).
cancer (continued). "In conclusion, our study uncovers an underlying mechanism by which BRCA1-deficient cancer cells resist apoptosis, and identifies possible therapeutic targets for BRCA1-mutated tumors." (PMID 35517499, 2022). "In HR repair-deficient cancers, which can result from BRCA1 and/or BRCA2 mutations, DNA damage cannot be repaired by either HR or the BER pathway, resulting in cell death." (PMID 36551731, 2022). "Mutations in BRCA1/2 genes have been found in some cancer types, including breast, ovarian, pancreatic, and prostate cancers." (PMID 36224343, 2022). "Despite promising clinical results for PARP inhibitors as single agents, particularly in cancers with BRCA1/2 mutations, the myelotoxicity and the high prevalence of acquired resistance remain challenges to more effective treatment." (PMID 35642638, 2022). "Prior studies also suggest a modest association between radiation exposure in mammograms, and elevated risk of cancer in BRCA1 mutation carriers." (PMID 35884402, 2022). "In contrast to sporadic cancers, TR receptors had prognostic significance in BRCA1-associated cancers but reverse correlations between TRα and TRβ." (PMID 35160139, 2022). "HRD due to loss of both BRCA1/2 alleles within cancer cells, and thus synthetic lethality when combined with PARP inhibitor use, will be tumor-specific and spare normal cells." (PMID 35205750, 2022). "Extending this to a multivariate pan-cancer analysis showed that CN17 was significantly associated with promoter hypermethylation of BRCA1 across cancer types, in addition to CN9." (PMID 35705804, 2022). "Cox proportional hazard model of DFS and OS analysis of BRCA1/2 mutation group were conducted on OV cohort with adjustment of diagnosis age, stage, and cancer grade." (PMID 35608067, 2022). "Proteins implicated in HR repair pathway were frequently mutated in human cancers, such as BRCA1/2, ATM/ATR, RAD51, FA proteins, and others." (PMID 35952757, 2022). "Many proteins that play pivotal roles in initiating and modulating HR have been identified, including the MRN complex, breast cancer susceptibility proteins (BRCA1 and BRCA2), ATM, and ATR (ataxia telangiectasia and rad3-related)." (PMID 36207426, 2022). "Considering the fact that BRCA1/2 mutations lead to impairment of HR mechanism, cancer cells are more prone to induction of the synthetic lethality." (PMID 35342397, 2022). "C3 and C5, the dividing cancer cells, expressed BRCA1 and BRCA2, whose variant and insufficiency lead to HRD." (PMID 35892844, 2022). "Mutations on tumor suppressor gene BRCA1 have been strongly linked to increased risks to breast, ovarian and other cancers." (PMID 35118379, 2022). "Pathway enrichment analyses showed genes implicated in cancer to be affected by TDs of which PTEN was found significantly more frequently affected by a TD in BRCA1-type BC." (PMID 35159019, 2022). "In summary, our study supports the suitability of pyridostatin for further clinical development, as a therapeutic strategy that can benefit cancer patients with BRCA1/2‐mutated and PARPi‐resistant disease." (PMID 35107878, 2022). "Recent studies have found that the FEN1-specific inhibitor Compound #8 is abnormally sensitive to cancers with BRCA1 and BRCA2 deficiencies." (PMID 35883563, 2022). "The risk for cancer in women with a germline pathogenic variant of BRCA1/2 is substantially elevated compared to the general population." (PMID 35190584, 2022). "Inherited mutations in BRCA1 are predisposed to an autosomal dominant predisposition to breast, ovarian, and other cancers." (PMID 36346676, 2022). "We initially analysed BRCA1 as proof-of-principle because its mutational landscape in cancer is well described and includes splicing mutations that have been repeatedly analysed." (PMID 35188075, 2022). "Cells with a defect in any component of HR are sensitive to treatment with PARP inhibitors, as exploited therapeutically in cancers where BRCA1 or BRCA2 are mutated." (PMID 35468497, 2022).
cancer (continued). "Unfortunately, the confounding factor of prior therapy with platinum is constant in many clinical trials with PARPi in PDAC, as well as in other BRCA1/2-associated cancer types." (PMID 35805011, 2022). "Data indicate that BRCA1/2 deficient cancers express higher levels of neoantigens, thereby making themselves more immunogenic." (PMID 35626165, 2022). "The target protein breast cancer type-1 susceptibility protein that belongs to BRCA1 gene was found from the literature." (PMID 34643844, 2022). "For example, BRCA1 and BRCA2 mutations and PARP inhibitors are synthetically lethal, which has become the conceptual basis for the new therapeutic paradigm of PARP inhibition for cancer patients carrying BRCA1 and BRCA2 mutations." (PMID 36011019, 2022). "If these findings are validated, the attitude should be taken into account in the treatment and preventive measures for BRCA1/2 mutation carriers with regard to cancer risk and prognosis." (PMID 35190584, 2022). "If cancer cells have underlying HR defects due to BRCA1/2 deficiency, they will be unable to repair DSB and finally die." (PMID 35281059, 2022). "This strategy holds true not only for BRCA‐1/2 deficient tumours, but hypoxic cancer cells demonstrate defective HR pathways, such as TNBC cells, which can be therapeutically exploited to induce greater radiosensitization." (PMID 35841287, 2022). "Mechanistically, mutations in BRCA1/2 inactivate the HR pathway, and in order to survive, BRCA1/2-mutated cancer cells require the activity of PARP1 in BER and/or a-NHEJ, to prevent the formation of DSBs from unrepaired SSBs during DNA replication." (PMID 36497275, 2022). "Cancers with BRCA1 and BRCA2 mutations have homologous recombination deficiency resulting in error‐prone repair of double‐strand DNA breaks and overall genetic instability." (PMID 35128817, 2022). "This is in line with BRCA1 being an estrogen-dependent cancer susceptibility gene, as loss of functional BRCA1 in cells tips the balance to proliferation and triggers tumorigenesis." (PMID 36231059, 2022). "Because PARPi resistance occurs frequently in cancer patients with BRCA1/2 mutations, there is a clinical need for new therapies, which can target resistant tumours." (PMID 35107878, 2022). "In a large cohort of the Chinese cancer population, the frequency of reversion mutations in pan-cancer unselected patients was 1.7%, with the most events reported in BRCA1, BRCA2, and PALB2 genes." (PMID 36557020, 2022). "Previous research has explored the naming preferences of adults for a cancer-related pathogenic variant, finding ‘faulty gene’ to be the preferred term among cancer patients, community members and men at high-risk of carrying a BRCA1/2 pathogenic variant." (PMID 36013276, 2022). "Newly diagnosed BRCA1/2 mutation carriers are offered various preventive options to counter their increased cancer risks." (PMID 35172875, 2022). "Regarding the therapeutic potential of modulating CST expression, CST has been found to promote PARP inhibitor sensitivity in BRCA1-deficient cancer cells." (PMID 35368664, 2022). "PARPis have been approved by the U.S. Food and Drug Administration (FDA) and the European Medicines Agency (EMA) for the treatment of several cancers with BRCA1/BRCA2 mutations, or other deficiencies in HR components." (PMID 36361678, 2022). "PARPi are effective therapeutic agents that induce synthetic lethality in HR-deficient cancers, which are most commonly caused by germline or somatic mutations in BRCA1/2 genes." (PMID 35270034, 2022).